LINC03004 (long independently transcribed non-coding RNA 3004)
Gene: Long non-coding RNA gene on chromosome 6 (137,647,887 to 137,777,092, forward strand). Ensembl gene ENSG00000230533.
Gene Ontology:
Biological process: miRNA-mediated post-transcriptional gene silencing
Cellular component: RISC complex